LCLAT1 (lysocardiolipin acyltransferase 1)
Description:
Exhibits acyl-CoA:lysocardiolipin acyltransferase (ALCAT) activity; catalyzes the reacylation of lyso-cardiolipin to cardiolipin (CL), a key step in CL remodeling (By similarity). Recognizes both monolysocardiolipin and dilysocardiolipin as substrates with a preference for linoleoyl-CoA and oleoyl-CoA as acyl donors (By similarity). Also exhibits 1-acyl-sn-glycerol-3-phosphate acyltransferase activity (AGPAT) activity; converts 1-acyl-sn-glycerol-3-phosphate (lysophosphatidic acid or LPA) into 1,2-diacyl-sn-glycerol-3-phosphate (phosphatidic acid or PA) by incorporating an acyl moiety at the sn-2 position of the glycerol backbone. Possesses both lysophosphatidylinositol acyltransferase (LPIAT) and lysophosphatidylglycerol acyltransferase (LPGAT) activities. Required for establishment of the hematopoietic and endothelial lineages (By similarity).
Synonyms: AGPAT8; ALCAT1; LYCAT; FLJ37965; LPLAT6; 1AGPAT8; HSRG1849; UNQ1849
Tractability: Antibody: UniProt predicts a signal peptide or a membrane-spanning region. PROTAC: ubiquitination databases record sites on it; its protein half-life has been measured.
Target class: Enzyme; Transferase
Gene: Protein-coding gene on chromosome 2 (30,447,221 to 30,644,225, forward strand). Ensembl gene ENSG00000172954.
Subcellular location: Endoplasmic reticulum membrane
Subcellular location (Human Protein Atlas): Endoplasmic reticulum; Cytosol
Pathways (Reactome):
Metabolism: Acyl chain remodeling of CL; Synthesis of PA
Gene Ontology:
Molecular function: 1-acylglycerol-3-phosphate O-acyltransferase activity; protein binding; acyltransferase activity, transferring groups other than amino-acyl groups; acyltransferase activity
Biological process: cardiolipin acyl-chain remodeling; phosphatidic acid biosynthetic process; phosphatidylinositol acyl-chain remodeling; CDP-diacylglycerol biosynthetic process; glycerophospholipid metabolic process
Cellular component: endoplasmic reticulum; endoplasmic reticulum membrane; membrane
Genetic constraint (gnomAD): Loss-of-function variants: 14 observed, 32.19 expected, observed/expected ratio (o/e) 0.43, 90% interval 0.29 to 0.68. The upper end of that interval is the gene's LOEUF score, 0.68, which puts it in group 2 of 6, group 1 being the genes least tolerant of losing a copy. Missense variants: 341 observed, 411.74 expected, observed/expected ratio (o/e) 0.83, 90% interval 0.76 to 0.91. Synonymous variants: 139 observed, 139.86 expected, observed/expected ratio (o/e) 0.99, 90% interval 0.87 to 1.14.
Homologues: Orthologues: chimpanzee LCLAT1 (99% identical), macaque LCLAT1 (98% identical), rabbit LCLAT1 (95% identical), guinea pig LCLAT1 (93% identical), dog LCLAT1 (93% identical), pig LCLAT1 (91% identical), rat Lclat1 (90% identical), mouse Lclat1 (89% identical), tropical clawed frog lclat1 (75% identical), zebrafish lclat1 (62% identical), Caenorhabditis elegans acl-8 (38% identical), Caenorhabditis elegans bus-18 (35% identical), and 1 more. Paralogues in human: AGPAT3 (26% identical), AGPAT5 (24% identical), AGPAT4 (23% identical), LPGAT1 (21% identical).
Diseases named in the same sentence as LCLAT1 in open-access papers:
LCLAT1 is named in the same sentence as 58 diseases in open-access papers, as found by Europe PMC text mining. Sharing a sentence is not in itself a finding about the gene and the disease. The quoted sentences say what the papers report.
Obesity (16 papers, 2014 to 2025). Accumulation of substantial excess body fat. "LCLAT1 has been studied in numbers of human diseases including obesity, cardiovascular diseases, and Parkinson’s diseases, but whether LCLAT1 plays a role in endometriosis remains unknown." (PMID 37393390, 2023).
Parkinson disease (5 papers, 2019 to 2025). A progressive degenerative disorder of the central nervous system characterized by loss of dopamine producing neurons in the substantia nigra and the presence of Lewy bodies in the substantia nigra and locus coeruleus. "For example, upregulation of LCLAT1 was shown to drive mitochondrial fission through the induction of Drp1, which led to subsequent impairment of mitochondrial respiration in a Parkinson’s disease model, similar to the results observed here for ETMR." (PMID 41473749, 2025).
steatosis (5 papers, 2020 to 2024). Increased lipid within the cytoplasm of cells. "Similarly, lysocardiolipin acyltransferase 1 (ALCAT1) has been found to link mitophagy defects to steatosis." (PMID 39183973, 2024).
cardiac hypertrophy (4 papers, 2021 to 2024). "Another one showed that the knockdown of lysocardiolipin acyltransferase 1 upregulates mitophagy to mitigate cardiac dysfunction associated with cardiac hypertrophy." (PMID 34631840, 2021). "Lysocardiolipin acyltransferase 1 (ALCAT1) deletion upregulates PINK1 and mitigates oxidative stress, insulin resistance, and mitochondrial dysfunction via activation of PINK1-mediated mitophagy and alleviating cardiac hypertrophy." (PMID 35096821, 2021).
Insulin resistance (4 papers, 2021 to 2025). Increased resistance towards insulin, that is, diminished effectiveness of insulin in reducing blood glucose levels. "These genes have been involved in insulin resistance and secretion (ATM, PTPRN2, PSMD10, and NSF), adipogenesis (SLC25A24 and PAX8), inflammatory processes (TNFRSF8 and SLIT3), and mitochondrial processes (PM20D1 and LCLAT1)." (PMID 36535927, 2022).
pulmonary fibrosis (4 papers, 2022 to 2025). Chronic progressive interstitial lung disorder characterized by the replacement of the lung tissue by connective tissue, leading to progressive dyspnea, respiratory failure, or right heart failure. "Similarly, LCLAT1, which regulates linoleic acid levels, affects mitochondrial function and reactive oxygen species (ROS) generation, contributing to pulmonary fibrosis." (PMID 37274115, 2023).
hepatocellular carcinoma (3 papers, 2023 to 2025). A malignant tumor that arises from hepatocytes. "Similarly, LCLAT1 expression was recently found to be upregulated in hepatocellular carcinoma (HCC), compared to normal liver tissue, and along with AGPAT5 and LPCAT1, was identified as a highly sensitive biomarker that correlated with worse prognosis and overall survival." (PMID 41473749, 2025). "First, we explored the expression of AGPAT5, LCLAT1, and LPCAT1 in common hepatocellular carcinoma cell lines by data mining in the CCLE database." (PMID 36845084, 2023). "When we knocked down both LCLAT1 and LPCAT1 in hepatocellular carcinoma cell lines, we could observe a significant increase in the protein level of E-cadherin." (PMID 36845084, 2023).
glioblastoma (2 papers, 2023 to 2025). The most malignant astrocytic tumor (WHO grade IV). "This group also compared LCLAT1 gene expression in pan-cancer tissues compared to normal tissue using the XENA-TCGA-GTEx datasets, finding overexpression in many tumors, including glioblastoma." (PMID 41473749, 2025). "In particular, AGPAT5, AGPAT6/GPAT4, AGPAT8/ALCAT1/LCLAT1, AGPAT9/LPCAT1, and AGPAT11/LPCAT2 show higher expression in glioblastoma tumors than in healthy tissue." (PMID 37046844, 2023).
lung carcinoma (2 papers, 2020 to 2024). "ALCAT1, a variant of LCLAT1, promotes mitochondrial fusion, proliferation, and migration of lung cancer cells and contributes to tumor growth during in vivo experiments." (PMID 38893234, 2024). "Elevated tumor expression of LCLAT1 is associated with a poorer prognosis in patients with this form of lung cancer." (PMID 38893234, 2024). "In the context of cancer, LCLAT1 expression is upregulated in lung cancer, particularly in lung adenocarcinoma." (PMID 38893234, 2024).
asthma (1 paper, 2023). "Researchers have found that changes in microRNA (miRNA) expression can contribute to the pathogenesis of asthma, and there is a negative correlation between LCLAT1 and miRNAs (miR-199b-5p and miR-223-3p) associated with asthma." (PMID 37875944, 2023).
congenital heart disease (1 paper, 2025). A heart disease that is present at birth. "Disruptions in the expression of Sirt5, Pfkm, and Lclat1 have been associated with mitochondrial dysfunction and also the onset of congenital heart disease, highlighting their importance in heart development." (PMID 41226629, 2025).
endometriosis (1 paper, 2023). The growth of functional endometrial tissue in anatomic sites outside the uterine body. "We detected elevated DRP1, OPA1, MFN2, and LCLAT1 in eutopic ESCs in patients with endometriosis than in controlled group." (PMID 37393390, 2023).
Hypertension (1 paper, 2020). The presence of chronic increased pressure in the systemic arterial system. "Promising candidate genes included CAPN13, a gene previously associated to hypertension in humans and LCLAT1, previously identified to control development of hematopoietic and endothelial lineages in mice embryos." (PMID 32719722, 2020).
non-small cell lung carcinoma (1 paper, 2023). A group of at least three distinct histological types of lung cancer, including non-small cell squamous cell carcinoma, adenocarcinoma, and large cell carcinoma. "Recently, LCLAT1 was identified as a partner gene for ALK in a patient with non-small cell lung cancer (NSCLC)." (PMID 36845084, 2023).
prediabetes (1 paper, 2025). "Compared to the control group, we detected 130 DMCs that were shared between the prediabetes and T2D groups, with LCLAT1, HLA-C, NINJ2, ZNF714, CNDP2, and HOOK2 among the top differentially methylated genes." (PMID 41373473, 2025). "A total of 130 DMCs across 99 genes, including LCLAT1, HLA-C, ZNF714, and HOOK2, were shared by prediabetes and T2D groups." (PMID 41373473, 2025).
prostate carcinoma (1 paper, 2025). A carcinoma that arises from epithelial cells of the prostate gland. "The same group also reported increased LCLAT1 expression in CNS, gastric, lung, and prostate cancers using the ONCOMINE database." (PMID 41473749, 2025).
cancer (7 papers, 2018 to 2025). A tumor composed of atypical neoplastic, often pleomorphic cells that invade other tissues. "DRP1-dependent mitochondrial fission has been widely considered as a regulator of cancer cell migration and invasion and LCLAT1 positively regulates DRP1 expression." (PMID 37393390, 2023). "Overexpression of LCLAT1 and subsequent CL fatty acyl chain remodeling is a known pathogenic driver in a number of metabolic diseases and non-CNS adult cancers." (PMID 41473749, 2025). "We explored the expression levels of AGPAT5, LCLAT1, and LPCAT1, the three core genes of the prognostic model, in normal and pan-cancer tissues based on XENA-TCGA-GTEx datasets." (PMID 36845084, 2023).
tumor (6 papers, 2017 to 2025). "In conclusion, our findings provide new mechanistic insights into ETMR biology and its reliance on mitochondrial fission and enhanced glycolysis for proliferation, as well as establish CL remodeling via LCLAT1 as a regulator of tumor suppressors and oncogenic proteins." (PMID 41473749, 2025). "Knockdown of LCLAT1 in HCC cell models impaired tumor cell proliferation, migration, and invasion." (PMID 41473749, 2025). "Finally, as mitochondrial dynamics and bioenergetics are known to regulate stem cell self-renewal and differentiation, we sought to investigate the impact of LCLAT1-driven CL remodeling on oncogenic, tumor suppressor, and neuronal differentiation pathways." (PMID 41473749, 2025). "We detected a structure-specific accumulation of cardiolipins and increased expression of the cardiolipin acyl chain remodeling enzyme, lysocardiolipin acyltransferase 1 (LCLAT1), within proliferating tumor cells in patient samples and the 3D tumorspheres." (PMID 41473749, 2025). "The results of tissue samples showed that AGPAT5, LCLAT1, and LPCAT1 were significantly upregulated in HCC tumor tissues than in adjacent normal tissues." (PMID 36845084, 2023). "High expression levels of LCLAT1 were detected in the embryonal tumor cells in all ETMR FFPE sections, regardless of the pathological presentation." (PMID 41473749, 2025). "Furthermore, we confirmed the ability of major members of this gene family to participate in tumor cell proliferation, migration, and invasion by silencing AGPAT5, LCLAT1, and LPCAT1, respectively, in HepG2 cell lines." (PMID 36845084, 2023). "The hazard ratios of LCLAT1 and CCDC43 are positive, indicating the anti- survival function of these genes, while the coefficients of other 5 genes are negative, including ENSG00000269386 (RAB11B-AS1), TOM1L2, AMPD3, MINK1 and WDTC1, indicating that they may be tumor suppressor genes." (PMID 28331188, 2017).
metabolic disease (5 papers, 2019 to 2025). A congenital disorder (due to inherited enzyme abnormality) or acquired (due to failure of a metabolically important organ) disorder resulting from an abnormal metabolic process. "The mechanistic pathways involved in pathological CL remodeling by LCLAT1 have primarily been investigated in these metabolic diseases and non-CNS tumors." (PMID 41473749, 2025).
infection (2 papers, 2014 to 2017). The state of being infected such as from the introduction of a foreign agent such as serum, vaccine, antigenic substance or organism. "Intriguingly, the expression of GPAT3 that encodes an enzyme that also converts LPA to PA, remained unchanged at 6 h but are subsequently downregulated as the infection proceeded, displaying an opposing expression pattern from LCLAT1 during late infection." (PMID 28993767, 2017). "Conversely, LCLAT1, which converts lysophosphatic acid (LPA) to phosphatic acid (PA), remained unchanged from mock-infected cells during early infection but was subsequently upregulated as the need for lipids increased." (PMID 28993767, 2017).
CNS tumors (1 paper, 2025). "Following KD of LCLAT1, we show altered CL acyl chain composition that resulted in a significant reduction in cell growth and proliferation, in agreement with the findings in non-CNS tumors." (PMID 41473749, 2025).
LCLAT1 also shares sentences with these, for which no sentence is quoted: myocardial infarction (8 papers); diabetes (6); cardiomyopathy (5); type 2 diabetes (4); fatty liver disease (3); heart failure (3); nonalcoholic fatty liver disease (3); cardiovascular diseases (2); diabetic kidney disease (2); acute myocardial infarction (1); Barth syndrome (1); brain tumors (1); breast carcinoma (1); Cirrhosis (1); colorectal cancer (1); coronary artery disease (1); diffuse intrinsic pontine glioma (1); diffuse midline glioma (1); embryonal tumors (1); ependymoma (1); glioma (1); head and neck squamous cell carcinoma (1); heart diseases (1); Hepatic steatosis (1); Hyperglycemia (1); hyperthyroidism (1); hypothyroidism (1); idiopathic pulmonary fibrosis (1); medulloblastoma (1); melanoma (1).
A further 7 diseases each share a sentence with LCLAT1 in 1 paper.